CD4 (CD4 molecule)
Diseases named in the same sentence as CD4 in open-access papers (continued):
Sharing a sentence is not in itself a finding about the gene and the disease.
tumor (continued). "In patients with HNSCC, tumours may achieve immune escape by reducing the number or altering the function of CD8+ T cells and CD4+ T cells." (PMID 40181975, 2025). "An EGFR‐Vδ2 bispecific T‐cell engagers (bsTCE) were developed to activate Vγ9Vδ2 T cells and selectively kill EGFR‐overexpressing tumor cells, which promoted the downstream activation of CD4+, CD8+ T cells and NK cells, but not Tregs." (PMID 40859900, 2025). "The tumor immune microenvironment (TIME), being critical in regulating tumor initiation, progression, and therapeutic responses, consisting of CD8+ T cells, CD4+ T helper cells, regulatory T cells (Tregs), B cells, natural killer T (NKT) cells, and tumor-associated macrophages (TAMs)." (PMID 40539049, 2025). "CD4+ T cells, Treg cells, and B cells mainly promote mitosis, recruit or activate myeloid cells, inhibit CD8+ T cells (CTLs), and directly or indirectly participate in tumor cell killing through auxiliary CTLs." (PMID 39895786, 2025). "Furthermore, MATE-expression by Ad5/11 was capable of breaking resistance to αPD-1 checkpoint therapy thereby promoting T-cell/tumor cell proximity and clustering of CD8+ and CD4+ T cells." (PMID 39789356, 2025). "Further analysis of CD4 T cell populations indicates that over 95% of CD4 T cells in LTS brains were CD4 T helper cells, and there was an 86.2% reduction in Tregs as compared to “Tumor” mice." (PMID 40379691, 2025). "The CD4/CD8 ratio, combined with nodal extracapsular spread, is associated with tumor recurrence but does not influence overall survival." (PMID 39860614, 2025). "This inversion of CD4+ and CD8+ T‐cell frequency in tumors compared with PB samples is mainly related to the marginal tumor area, in fact, we observed a significantly lower CD4+ T‐cell frequency in the margin compared with PB, while the intense and core layers displayed frequencies similar to PB." (PMID 40498413, 2025). "Notably, the SASP from tumor cells can recruit and activate CD4(+) and CD8(+) T cells, providing anti-tumor protection." (PMID 40149983, 2025). "Therefore, future PTT-mediated anti-tumor immunotherapy targeting B cells will emphasize enhancing B cell antigen presentation and inhibiting the TGF-β differentiation of CD4+ T cells." (PMID 40688079, 2025). "Spatial analyses of immune cell infiltrates by multiplex immunohistochemistry indicated an improved proximity of CD8+ T cells, but not CD4+ T cells, with cancer cells enhancing the probability of immunological synapse formation and tumor cell killing." (PMID 39789356, 2025). "As an adjuvant for peptide vaccines, NVT/SM-LNP enhances antigen-specific CD4+ and CD8+ T cell responses and demonstrates potent therapeutic efficacy across subcutaneous, orthotopic, and metastatic TC-1 and B16-OVA tumor models, while also reducing viral titers in a chronic LCMV infection model." (PMID 41436456, 2025). "Overall, the breadth of immuno-PET tracers now being investigated—ranging from PD-L1-directed agents to those targeting CD8, CD4, or CD11b—addresses critical, nonoverlapping aspects of tumor–immune interactions." (PMID 41019666, 2025). "Thus, increased naive CD4+ and memory CD8+ T cells and expanded TH2 and diminished TH17 populations were the characteristics of tumor-infiltrating T cells under combination therapy." (PMID 40897896, 2025). "Additionally, it increases CD4+ and CD8+ T cell infiltration, enhances CD8+ T cell activation, reduces exhaustion, and decreases Tregs in the tumor." (PMID 40366419, 2025). "Here, we demonstrate that CD4+ but not CD8+ anti-TGF-β CAR T cells (T28zT2 T cells) can suppress tumor growth partly through secreting Granzyme B and interferon (IFN)-γ." (PMID 40107245, 2025). "In contrast, the efficacy of combined aCD40 and ICB treatment required both CD4 + and CD8 + T cells along with cDC1s for primary tumor rejection, highlighting the cooperative nature of these immune populations in mediating maximal therapeutic responses in the context of combination immunotherapy." (PMID 40585246, 2025).
tumor (continued). "Therefore, the combined assessment of CD3, CD4, and CD8 patterns provides a more robust framework for understanding how interactions between these subpopulations affect the immune response in the tumor context." (PMID 41383591, 2025). "To note, we observed an accumulation of 64Cu-CD4-Nb1 preferentially at the tumor margins of nontreated PyMT tumors." (PMID 40561008, 2025). "In addition, immunohistochemical analysis revealed that tumor cells were positive for CD3, CD43, CD56, TIA1, granzyme B, CD2, CD4, and CD7." (PMID 40433378, 2025). "In instances, tumour‐bearing mice being sensitive to anti‐PD1 antibody were administered with anti‐PD1 therapy and subsequently occurred to relapse, a compromised immune status was observed, characterized by diminished CD8+, CD4+ and GZMB+ levels." (PMID 40356247, 2025). "In CLL, evidence suggests the presence of multiple clones of leukemia-reactive CD4+ and CD8+ T cells in patients, indicating that a vaccine approach using whole tumor cells may be more effective than one targeting a single antigen." (PMID 40382583, 2025). "Our study demonstrates that C1QC+ RTMs may promote CD4+ T cell activation through MHC-II molecules, thereby enhancing anti-tumor immunity and benefiting immunotherapy." (PMID 40593467, 2025). "In the tumor microenvironment, MDSCs were shown to inhibit the anti-tumor impact of adaptive immune responses, specifically the tumor elimination capability of CD8+ and CD4+ T cells." (PMID 40563574, 2025). "In addition, we further assessed the changes in CD4+ T and CD8+ T cells in the tumor microenvironment using immunohistochemistry." (PMID 40497373, 2025). "Numerically higher CD4+ and CD8+ T-cells and significantly higher CD20+ B-cells in the tumor immune microenvironment at baseline support the local immunostimulatory effect of the treatment and were associated with improved clinical outcomes to trametinib and pembrolizumab." (PMID 40486486, 2025). "We thus speculated that RHRT may induce the release of neoantigens by tumor cells that in turn stimulated the priming and expansion of neoantigen-specific T cells, represented by the boosted PD-1+ CD8+ and CD4+ T cells observed in the periphery." (PMID 40236706, 2025). "Notably, R. gnavus supplementation potentiates anti-PD-1-mediated tumor elimination in mice by inducing a proinflammatory intestinal microenvironment, which enhances the proliferation and infiltration of TNF-producing CD4+ T cells into tumors." (PMID 40770084, 2025). "Furthermore, we observed higher percentages of tumor-infiltrating IFN-γ+ and GZMB+, CD107a+ cytotoxic CD8+ T cells and IFN-γ+ CD4+cells in AgkcKO mice compared with their counterparts in Agkfl/fl mice." (PMID 39816692, 2025). "Furthermore, CD4+ T cells have been shown to influence the differentiation, survival, and functionality of CD8+ T cells, which are the primary effectors of tumor killing." (PMID 40177538, 2025). "We then compared the most abundant immune cell types and found that naïve B-cells (rank = 8) and naïve CD4 T cells (rank = 10) ranked within the top 10 of the peripheral tumor microenvironments but were not in the top 10 of the infiltrated spots." (PMID 40510374, 2025). "Furthermore, interferon-gamma (IFN-γ), a type II interferon with antiviral, antitumor, and immunomodulatory properties, is produced by immune cells such as CD4+ and CD8+ tumor-specific T lymphocytes." (PMID 40005446, 2025). "In the group receiving 12.5 mg/kg of MP4, Treg populations (CD4+FoxP3+) were reduced by 50% in tumor samples, but not in blood and spleen, indicating a more specific targeting of Tregs in the TME contributing to the anti-tumor immune response." (PMID 40034859, 2025). "The mean percentages of LAP+ cells in CD4+ T cells, CD8+ T cells, B cells, and granulocytes significantly increased on day 7 after tumor inoculation (29.7%, 32.9%, 35.1%, and 50.4%, respectively) and they decreased on day 34 (16.4%, 16.9%, 24.7%, and 10.9%, respectively)." (PMID 40053558, 2025).
tumor (continued). "Meanwhile, CD4+ T cells activated by tumor antigens presented on MHC class II molecules enhance the activity of CD8+ T cells, promote MHC class I expression on tumor cells, stimulate cytotoxicity of myeloid cells, and finally contribute to the targeted destruction of tumor cells." (PMID 39941745, 2025). "CD4+ T cells are activated through MHC class II presentation of peptide antigen by DCs and play a key supportive role in coordinating and optimizing anti-tumor CTL responses." (PMID 41542091, 2025). "CD69− populations among CD4+ T cells were less frequent in both tumor and non-tumor tissues of alcohol-related HCC patients (p < 0.05)." (PMID 40361474, 2025). "We quantitatively assessed the infiltration of various tumor immune cells in the tumor center and invasive margins, including CD45+ leukocytes, CD3+ and CD8+ cytotoxic T cells, CD4+ helper T cells, CD45RO+ activated and memory T cells, and FOXP3+ regulatory T cells." (PMID 40240758, 2025). "Using the OMIQ platform and CyTOF, they characterized tumor immune infiltration and found that MC38 and YUMMER2.1 cells with B2M KO responded to anti-PD-1 treatment alone or in combination with IL-2 agonists, mediated by CD4+ T cells and NK cells." (PMID 40191187, 2025). "Recently Nature also reported the existence of a stem-like CD4+ T cells within TDLNs that are capable of differentiating into CD4+ TH1 cells and promoting effector differentiation of CD8+ T cells by secreting IFN-γ, thereby controlling tumor growth and improving response to ICI therapy." (PMID 40385461, 2025). "An excessive amount of CD4 + CD25 + Tregs can lead to immune escape and promote tumor development." (PMID 40587482, 2025). "Pathological evaluation of patient samples revealed substantial T cell enrichment in tumor tissues post-chemotherapy, with significantly higher densities of CD3+, CD4+, and CD8+cells in treated compared to untreated groups (P = 0.0057, 0.031, and 0.031, respectively)." (PMID 41488631, 2025). "Further, the ratio of total TCRβ+CD8 + T cells to total GFP + Tregs (among TCRβ+CD4+ cells) was increased in the tumor (albeit not spleen) of Foxp3Cre-ERT2Pik3c3fl/fl mice, indicating enhanced anti-tumor immunity." (PMID 40215232, 2025). "Based on the flow cytometry, a significant increase in absolute count of CD3, CD4+T cells, CD8+T cells along with CD19+B cells, natural killer cells, and M1 macrophages per mg of tumor was observed in the CBD-treated tumor tissues compared to the vehicle-treated group." (PMID 40475776, 2025). "Given BGC cells and CD4 + Tfh cells are essential components of TLS and functionally interact with each other, we analyzed lineage-normalized cell-type frequencies to explore these interactions within the tumor microenvironment." (PMID 40287532, 2025). "Therefore, we evaluated the tumor infiltration levels of CD8+ T cells, CD4+ T cells, neutrophils, and macrophages in LUAD samples with varying somatic copy number alterations of CRABP2." (PMID 39991584, 2025). "This study observed an increase in the proportion of CD4+ T lymphocytes, suggesting that ACE may inhibit tumor growth by promoting Th17 differentiation." (PMID 40417009, 2025). "In addition, the results of immunofluorescence staining showed that CD4+ and CD8+ T cells in tumor tissues from the MMW treatment groups, particularly in the combined treatment group, were significantly elevated." (PMID 41383334, 2025). "Additionally, this triple therapy increased the frequency of T-bet + CD8 + tumor-infiltrating lymphocytes (TILs) within the tumor microenvironment (TME), enhanced the frequency of CD4+ ICOS+ T cells, promoted granzyme B production, and reduced PD-1 expression." (PMID 41024300, 2025). "Dimensionality reduction and clustering analysis identified 14 cell lineages, including CD4 memory T cells, CD8 T cells, Plasma, Tregs, Epithelial tumor cells, activated B, Macro_Mono, Endothelial Cell, CAFs, T cells, B cells, MEP, Memory B cells, and DC cells." (PMID 40959083, 2025).
tumor (continued). "Additionally, IgE promotes antigen presentation through interactions with dendritic cells and B cells, thereby activating CD4 + and CD8 + T cells and further amplifying the anti-tumor immune response." (PMID 40740961, 2025). "Although γδ T cells and CD4 T cells express cytotoxic genes (e.g., GZMB, NKG7), their activity may be suppressed by tumor-induced immune checkpoint signaling and metabolic competition." (PMID 40340807, 2025). "In comparison with B cells, agonist treatments did not significantly increase tumor infiltration of CD4+ or CD8+ T cells." (PMID 40897896, 2025). "However, in the tumor region, the proportions of CD20+Ki-67+ B cells, CD21+ cells, and CD4+Ki-67+ Th cells were higher in the NRCI group than in the NCI group when the T score was 1 (percentage: all P<0.05)." (PMID 40918107, 2025). "The proportions of CD4+ TEM cells, CD8+ TEM cells, CD4+ TCM cells, and CD8+ TCM cells were all significantly elevated, while glucose consumption was amplified in the cell cycle, leading to the dual effects of glucose metabolism and tumor immunotherapy." (PMID 40698137, 2025). "We found a significantly varying abundance of immune cell subsets across tumor types, which was largely due to significantly elevated levels of CD4+ T cells (p = 0.03), CD8+ T cells (p = 0.04), other CD4+ cells (p = 0.03), and unclassified immune cells (p = 0.04) in ACC." (PMID 41083996, 2025). "Similar to CD4+ cells, intratumoral CD8+ cell infiltration significantly increased (p < 0.05) after the treatment with GSE and AA by 11.8% and 10.89%, respectively, compared to tumor sections from the SEC group." (PMID 40843004, 2025). "A study utilizing Dectin-3 knockout mice revealed that the absence of this receptor led to enhanced tumor growth, accompanied by increased macrophage glycolysis and reduced infiltration of CD4+ and CD8+ T cells." (PMID 41163402, 2025). "Highly attenuated, live Lm strains, engineered to express tumor associated antigens (TAA) fused to a truncated LLO, can therefore induce potent anti-tumor CD8+ and CD4+ T cell responses that break peripheral tolerance and lead to regression of target-antigen+tumors." (PMID 39958231, 2025). "CD4+ helper T cells, CD8+ cytotoxic T cells, NK cells and in certain cases, neutrophils contribute to immune surveillance of tumour cells, whereas other immune cells, such as regulatory T cells and certain myeloid cell subsets, were reported to suppress anti-tumour immune responses." (PMID 39567755, 2025). "Further, depletion of CD8+, but not CD4+, T cells significantly abolished the anti-tumor activity of the AT406 and anti-PD1 combination treatment, suggesting the underlying immune killing effect and CD8+ T cell-dependency." (PMID 40057483, 2025). "In contrast to the spleen and TDLNs, there was almost a complete lack of naïve CD4+ T cells in the control tumor, a situation that was reversed by all 3 types of therapy, with IGRT/TAT/immunocytokine therapy exhibiting the most dramatic increase." (PMID 40813233, 2025). "Accordingly, it was found that transfer of CD8 T cells but not CD4 or CD19 was capable of inducing protection from LLC tumor cells." (PMID 41316207, 2025). "Conversely, TUBA1B expression negatively correlated with immune killer cells, including NK/NKT cells, CD4+ T cells, and CD8+ T cells, which are essential for anti-tumor immunity, indicating that elevated TUBA1B levels may inhibit effective immune responses." (PMID 39968182, 2025). "The expression levels of ALG3 in tumor cells and stromal cells were positively correlated with the abundance of CD4+ FOXP3+ regulatory T cells (Tregs), CD3+CD4+ T cells and PD-L1, whereas they were negatively correlated with the abundance of CD8+ T cells and CD68+CD86+ macrophages." (PMID 40475760, 2025). "Specifically, CD4, CD8 T cells, and regulatory T cells (Tregs) showed comparable abundances in UA and resection samples, suggesting that UA adequately reflects the tumor tissue for these T-cell subsets." (PMID 40002198, 2025).
tumor (continued). "We strategically selected regions of interest based on TLS staining on consecutive slides by employing a combination of CD4/CD8/CD20/CD23 multiplex immunofluorescence (mIF) to identify mTLSs and CD45/PanCK morphologic markers to locate the tumor or stromal area." (PMID 39909044, 2025). "Furthermore, Gal-9 expression on blood-derived CD4+ and CD8+ T cells has been found to correlate with tumor size, lymph node metastasis, and UICC stage." (PMID 39958335, 2025). "In melanoma, this approach revealed superior anti-tumor efficacy of rigosertib over anti-PD-1 therapy, including improved modulation of CD8+/CD4+ T cell ratios, highlighting the need for optimized immune-editing models to accurately assess therapeutic responses." (PMID 41050070, 2025). "Specifically, the authors examined the status of CD3(+), CD4(+), CD8(+), CD20(+), and CD68(+) cells separately in the tumor center and the invasive front and demonstrated that increased CD3(+) T cell density at the tumor center is associated with a favorable response to neoadjuvant chemotherapy." (PMID 40243442, 2025). "High C5a levels stimulate linfoma with decreased infiltration of CD4+ and CD8+ T cells, while low levels of C5a in the TME decrease tumor progression, thus, the local concentration of C5a, independent of complement activation, seem to be critical to determine its role in tumor progression." (PMID 40370471, 2025). "Reduced the tumor volume;increased infiltration of CD8+ T, CD4+ T and Tregs cells." (PMID 40698086, 2025). "Our studies show that CD4+ T cells also have a direct cytolytic role against tumor cells, which is non-cell-autonomously activated by the RCOR2–HDAC1/2–CIITA–MHC-II axis in tumor cells." (PMID 40608411, 2025). "Indeed, anti–PD-1 therapy increased the levels of IL-21 in BALF of tumor-bearing aged mice, which was disrupted by ICOSL blockade, and lung-infiltrating ICOS+CD4+ T cells in anti–PD-1 Ab–treated aged mice had an ability to produce IL-21." (PMID 40198121, 2025). "In addition to B cell recruitment, PreS1‐pHLIP NMs significantly increased intratumoral CD3+, CD3+CD4+, and CD3+CD8+ T cell populations, indicating the mobilization of T cell‐mediated immunity for tumor elimination." (PMID 40091501, 2025). "To assess the impact of the drugs on T cell phenotypes, we detected the CAR-T cell positive rate and the CD8+/CD4+ CAR-T cell ratio after co-culture with tumor cells with or without RSL3." (PMID 39849645, 2025). "Consistent with literature, since the mice treated with the combination therapy exhibited increased CD4+/CD8+ pro-inflammatory cytokines and an abundance of infiltrating CD8+ T-cells within the tumor microenvironment, this change resulted in necrosis and pseudo-progression." (PMID 41008842, 2025). "CD4+ and CD8+ T cells possess the potential to exert an anti-tumor effect on tumor metastasis." (PMID 39834121, 2025). "Immune-derived data, particularly the characterization of the tumor microenvironment (TME) and peripheral immune cell populations (e.g., circulating PD-1+ CD4+ effector memory T cells), have emerged as independent predictors of progression-free survival and response to ICIs." (PMID 41374434, 2025). "Overall, CD4+ T cells in the TME of BC are emerging as key actors not only in supporting CD8+ T cell responses but also in directly engaging in tumor cell killing." (PMID 40177538, 2025). "In our bulk analysis, high CD4/CD8 expression was observed in 52% of tumors with high CD40 expression, suggesting that CD40 was expressed not only in T cells but also in tumor cells within the tumor microenvironment." (PMID 41182434, 2025). "Furthermore, altered immune cell infiltration, such as decreased activation of CD4 and CD8 T cells upon SMC4 inhibition, highlights the intricate balance between tumor cell death pathways and immune surveillance." (PMID 39949776, 2025).